SACM1L (SAC1 like phosphatidylinositide phosphatase)
Description:
Phosphoinositide phosphatase which catalyzes the hydrolysis of phosphatidylinositol 4-phosphate (PtdIns(4)P). Can also catalyze the hydrolysis of phosphatidylinositol 3-phosphate (PtdIns(3)P) and has low activity towards phosphatidylinositol-3,5-bisphosphate (PtdIns(3,5)P2) (By similarity). Shows a very robust PtdIns(4)P phosphatase activity when it binds PtdIns(4)P in a 'cis' configuration in the cellular environment, with much less activity seen when it binds PtdIns(4)P in 'trans' configuration. PtdIns(4)P phosphatase activity (when it binds PtdIns(4)P in 'trans' configuration) is enhanced in the presence of PLEKHA3.
Synonyms: KIAA0851; SAC1
Tractability: Antibody: UniProt predicts a signal peptide or a membrane-spanning region. PROTAC: ubiquitination databases record sites on it; its protein half-life has been measured.
Target class: Enzyme; Hydrolase
Safety:
Unwanted effects reported when the protein is acted on. In parentheses: how it was acted on, where the effect was seen, and who reports it.
sexual side-effects (source: ClinPGx)
Gene: Protein-coding gene on chromosome 3 (45,689,056 to 45,745,425, forward strand). Ensembl gene ENSG00000211456.
Subcellular location: Endoplasmic reticulum membrane; Golgi apparatus membrane
Subcellular location (Human Protein Atlas): Golgi apparatus; Nucleoplasm
Pathways (Reactome):
Metabolism: Synthesis of PIPs at the ER membrane; Synthesis of PIPs at the Golgi membrane
Gene Ontology:
Molecular function: phosphatidylinositol-4-phosphate phosphatase activity; protein binding; phosphatase activity; phosphatidylinositol phosphate 4-phosphatase activity; phosphatidylinositol-3-phosphate phosphatase activity
Biological process: phosphatidylinositol dephosphorylation; phosphatidylinositol biosynthetic process; exocytic insertion of neurotransmitter receptor to postsynaptic membrane
Cellular component: endoplasmic reticulum membrane; endoplasmic reticulum-plasma membrane contact site; Golgi apparatus; Golgi membrane; AMPA glutamate receptor complex; glutamatergic synapse
Genetic constraint (gnomAD): Loss-of-function variants: 7 observed, 25.68 expected, observed/expected ratio (o/e) 0.27, 90% interval 0.15 to 0.51. The upper end of that interval is the gene's LOEUF score, 0.51, which puts it in group 2 of 6, group 1 being the genes least tolerant of losing a copy. Missense variants: 185 observed, 262.27 expected, observed/expected ratio (o/e) 0.71, 90% interval 0.62 to 0.8. Synonymous variants: 87 observed, 92.97 expected, observed/expected ratio (o/e) 0.94, 90% interval 0.79 to 1.12.
Homologues: Orthologues: chimpanzee SACM1L (99% identical), macaque SACM1L (99% identical), rabbit SACM1L (96% identical), mouse Sacm1l (95% identical), rat Sacm1l (95% identical), dog SACM1L (94% identical), pig SACM1L (94% identical), guinea pig SACM1L (94% identical), tropical clawed frog sacm1l (84% identical), zebrafish sacm1lb (80% identical), zebrafish sacm1la (78% identical), Caenorhabditis elegans sacm-1L (46% identical), and 1 more. Paralogues in human: INPP5F (18% identical), INPP5D (17% identical), INPPL1 (17% identical), FIG4 (16% identical), SYNJ1 (16% identical), INPP5B (15% identical), SYNJ2 (15% identical), OCRL (14% identical), INPP5J (12% identical), INPP5E (11% identical), INPP5K (8% identical), SH2D1B (4% identical), and 1 more.
Diseases named in the same sentence as SACM1L in open-access papers:
SACM1L is named in the same sentence as 15 diseases in open-access papers, as found by Europe PMC text mining. Sharing a sentence is not in itself a finding about the gene and the disease. The quoted sentences say what the papers report.
COVID-19 (3 papers, 2022 to 2024). A disease caused by infection with severe acute respiratory syndrome coronavirus 2. "Among other genes with altered expression levels caused by rs17713054 and rs17078346 is SACM1L, which was previously identified as a putative causal gene for COVID-19 severity." (PMID 39175753, 2024). "Our study also replicated a previously reported COVID-19 risk locus at 3p21.31, identifying lead variants in SACM1L and LZTFL1 genes suggestively associated with pneumonia (p = 7.54 × 10−6) and severe COVID-19 (p = 6.88 × 10−7), respectively." (PMID 35910207, 2022). "Our genome-wide analysis detected a suggestive signal in replicated COVID-19 risk locus at chromosome 3p21.31, in the 3′-UTR of the SACM1L gene (OR = 0.084, 95% CI: 0.028–0.257, p = 7.54 × 10−6)." (PMID 35910207, 2022). "CCRL2, LZTFL1, SCAP, and SACM1L are also differentially expressed in at least one experiment that measures differential expression of genes in lung tissues and related cell lines infected with COVID-19 or other viruses that stimulate similar immune responses." (PMID 36763080, 2023). "Detected lead SACM1L rs73060324 variant highly correlates with rs17279437 missense variant (r2 = 0.88) located in the SLC6A20 gene, a potential causative candidate which has been previously associated with COVID-19." (PMID 35910207, 2022).
Obesity (1 paper, 2024). Accumulation of substantial excess body fat. "We found that six genes (Sacm1l, Junb, Bmi1, Erbb4, Dkc1, and Suv39h1) are neuron stress-related genes and increased in the HFD-induced mice obesity model, Bmi1gene was identified as a key genes that can reflect the pathophysiology of obesity." (PMID 39717104, 2024).
infection (5 papers, 2021 to 2025). The state of being infected such as from the introduction of a foreign agent such as serum, vaccine, antigenic substance or organism. "Furthermore, only 30% of Salmonella was localized to LysoView+ acidic compartments in SACM1L KO cells at 120 min post-infection as compared to 44% in WT cells, confirming that SAC1 loss delays the fusion of Salmonella-containing autophagosomes with lysosomes." (PMID 34320354, 2021). "The percentages of both MagicRed+ and DQ-BSA+Salmonella by 2 h post-infection were lower in SACM1L KO cells than in WT cells." (PMID 34320354, 2021). "A higher percentage of Salmonella was associated with endogenous LC3, NDP52, and SQSTM1 at 2 h post-infection in SACM1L KO cells than in WT cells, suggesting a delay in Salmonella-containing autophagosome maturation." (PMID 34320354, 2021). "Additionally, the percentage of LC3+Salmonella was higher in SACM1L KO cells than in WT cells at 2 h post-infection, which is indicative of a delay in autophagosomal maturation and LC3 turnover." (PMID 34320354, 2021). "Furthermore, treatment with the PI4K2ɑ-specific inhibitor PI-273 suppressed accumulation of LC3 and ubiquitin, which serve as markers for autophagosomal maturation, on Salmonella in SACM1L KO cells at 2 h post-infection." (PMID 34320354, 2021). "Furthermore, re-expression of SAC1 WT, but not SAC1 C389S or BFP, reduced the levels of NDP52+, SQSTM1+, and LC3+Salmonella in SACM1L KO cells at 2 h post-infection, revealing that SAC1 phosphatase activity is necessary for functional xenophagy." (PMID 34320354, 2021). "To evaluate Salmonella existing within these compartments, we monitored WT and SACM1L KO cells co-expressing GFP-LC3 (marking autophagosomes) and LAMP1-mCherry (marking SCVs) by live cell imaging for 6 h post-infection." (PMID 34320354, 2021). "We monitored the dynamic recruitment of GFP-tagged Gal3 to intracellular dsRed-expressing Salmonella but did not detect differences in co-localization in WT and SACM1L KO cells, suggesting that the loss of SAC1 does not affect SCV integrity at 1 h post-infection." (PMID 34320354, 2021).
cancer (2 papers, 2022 to 2023). A tumor composed of atypical neoplastic, often pleomorphic cells that invade other tissues. "Mutation of SACM1L, a gene for phosphatidylinositol-3-phosphatase SAC1, is common among cancers." (PMID 37892232, 2023).
tumor (2 papers, 2017 to 2023). "CNAs of 257 genes such as LIMD1-AS1 and SACM1L at 3p21.31 classified 10 and more G1 tumours in respect to G3 tumours, see Table P in S2 File." (PMID 28486536, 2017). "Comparing the tumour grades G1 and G3 in respect to gene losses, LIMD1-AS1 and SACM1L at 3p21.31 together with additional genes at 3p21.31, 3p21.1, 3p22.1, 3p22.3, 3p25.1 and 3p25.3 underscore that losses of these genes/chromosomal segments favour the establishment of grade G1 ccRCC tumours." (PMID 28486536, 2017).
heart disease (1 paper, 2013). "Although the intronic splicing site mutation in the SACM1L gene has not been linked to heart disease, its effect on protein function could not be predicted by either dbNSFP or SIFT 2013." (PMID 24349489, 2013).
SACM1L also shares sentences with these, for which no sentence is quoted: amyotrophic lateral sclerosis (1 paper); diabetic foot ulcer (1); Hypertension (1); leukemia (1); malaria (1); Onset (1); Parkinsonism (1); pneumonia (1); Salmonella Infections (1).